RNU5A-5P (RNA, U5A small nuclear 5, pseudogene)
Gene: Small nuclear RNA gene on chromosome 1 (231,670,635 to 231,670,750, forward strand). Ensembl gene ENSG00000222986.
Homologues: Orthologues: chimpanzee U5 (99% identical), macaque U5 (84% identical). Paralogues in human: RNU5A-2P (72% identical), RNU5A-6P (72% identical), RNU5E-4P (71% identical), RNU5B-2P (70% identical), RNU5E-7P (70% identical), RNU5E-10P (69% identical), RNU5E-5P (69% identical), RNU5F-4P (68% identical), RNU5E-8P (66% identical), RNU5F-7P (66% identical), RNU5A-7P (65% identical), RNU5E-9P (65% identical), and 13 more.